RN7SL153P (RNA, 7SL, cytoplasmic 153, pseudogene)
Gene: Miscellaneous RNA gene on chromosome 5 (72,314,397 to 72,314,688, reverse strand). Ensembl gene ENSG00000244748.
Homologues: Orthologues: chimpanzee Metazoa_SRP (98% identical), macaque Metazoa_SRP (91% identical), dog Metazoa_SRP (67% identical). Paralogues in human: RN7SL1 (80% identical), RN7SL2 (80% identical), RN7SL3 (80% identical), RN7SL451P (78% identical), RN7SL556P (77% identical), RN7SL478P (77% identical), RN7SL513P (77% identical), RN7SL543P (77% identical), RN7SL300P (77% identical), RN7SL492P (77% identical), RN7SL655P (77% identical), RN7SL147P (76% identical), and 700 more.